CDK5 (cyclin dependent kinase 5)
Diseases named in the same sentence as CDK5 in open-access papers (continued):
Sharing a sentence is not in itself a finding about the gene and the disease.
tumor (continued). "Cyclin-dependent kinase 5 (CDK5) is a proline-directed serine/threonine kinase that functions as tumor promoter in the development and progression of multiple cancers by regulating cell proliferation, apoptosis, DNA repair and immune escape." (PMID 31496920, 2019). "We investigated how the transient silencing of Cdk5 affected three important characteristics of tumor cells: proliferation, migration and invasion." (PMID 31614664, 2019). "Consistent with our observations in human HCC tumor tissues, the expression levels of CDK5 were also highly upregulated in DEN-treated livers compared with control livers by western blotting and immunostaining." (PMID 31272499, 2019). "To clarify the tumorigenesis mechanisms of CDK5, we constructed a tumor-bearing mouse model by injecting H460 cells into BALB/c nude mice." (PMID 31496920, 2019). "In CRC, Cdk5 functions as a tumor promoter via modulating the extracellular receptor kinase 5 (ERK5)—activator protein 1 (AP-1) axis and it has been associated with oxaliplatin resistance acquisition." (PMID 31614664, 2019). "In cohort A, Cdk5 and p35 proteins were clearly overexpressed as detected by western blot in tumor tissues as compared to the corresponding normal adjacent tissues." (PMID 31614664, 2019). "Conversely, CDK5 knockdown in a xenograft mouse model increased the p21CIP1 protein level and retarded tumor growth." (PMID 31395805, 2019). "The kinase activity of CDK5 was necessary for tumor progression, and the promoting effect of CDK5 was dependent on its substrate TPX2." (PMID 31272499, 2019). "miR-27a was considered as a tumor suppressor in MM and leukemia as it targeted oncogenes, CDK5 and P-glycoprotein, which were highly expressed in tumor cells." (PMID 30405034, 2018). "To confirm inhibition of CDK5 in vivo, we performed western blot analyses on the tumor lysates with tumors from three representative animals from each treatment group." (PMID 29435174, 2018). "Additional analyses that compared normal tissue with corresponding primary tumor revealed that of the 31 patients examined, all but two showed a significant increase in CDK5 levels in primary tumors when compared to normal colon tissue." (PMID 29435174, 2018). "Recent studies have validated CDK5 as a tumor promoter and designated it as a therapeutic target for CRC therapy." (PMID 29435174, 2018). "Our immunohistochemistry results revealed increased CDK5 expression levels in HCC patients with tumor metastasis, vascular invasion, portal vein tumor embolus, moderate differentiation and higher clinical TNM stages." (PMID 29312535, 2017). "MiR-27a was identified as a tumor suppressor to be downregulated in MM and leukemia cells and targeted the oncogenes CDK5 and P-glycoprotein, respectively, which were highly expressed in tumor cells culminating in the same outcome as above." (PMID 28623912, 2017). "CDK5 expression was significantly increased in HCC tissues (n=1630) compared with non-tumor tissues (n=1688) based on 26 of these datasets." (PMID 29312535, 2017). "This set of data suggests that Cdk5 indeed is the primary target of roscovitine, but that roscovitine also acts on tumor cells as well and inhibits other Cdks besides Cdk5." (PMID 26755662, 2016). "We have previously shown that treatment of HUH7 tumors with roscovitine (rosco), a well-established CDK5 inhibitor, or downregulation of CDK5 by siRNA in HCC cells, causes reduction of tumor growth to about one half or less." (PMID 27027353, 2016). "In fact, Cdk5 inhibition can sensitize tumors to conventional anti-angiogenic treatment as shown in tumor xenograft models." (PMID 26755662, 2016). "A research stated that CDK5 was mandatory for the DNA damage response in tumor cells and another study showed that CDK5/STAT-3 oncogenic pathway played a key role in the expression of DNA repair genes." (PMID 27406233, 2016).
tumor (continued). "To investigate the influence of Cdk5 inhibition on tumor growth in a more therapeutic context, we used systemic treatment with the small molecule Cdk5 inhibitor roscovitine." (PMID 26755662, 2016). "In conclusion, our findings help provide evidence that elevated CDK5 in human CRC has an important role in the acquisition of the progression as well as poor prognosis of the tumor." (PMID 27735944, 2016). "We have recently shown that stable knockdown of CDK5 in HUH7 cells by shRNA reduces tumor growth in vivo." (PMID 27027353, 2016). "In sum, the present study elucidates an essential in vivo role of Cdk5 in tumor angiogenesis suggesting Cdk5 inhibition as a novel approach for anti-angiogenic treatment." (PMID 26755662, 2016). "We then characterize tools for the best CDK5 substrate we identified to monitor its phosphorylation in human tissue and use these to interrogate human tumour arrays." (PMID 26555036, 2015). "In medullary thyroid carcinoma (MTC), CDK5, p35 and p25 are highly expressed, and CDK5 promotes tumorigenesis and tumor progression via down-regulating its downstream target, Retinoblastoma gene (Rb)." (PMID 26690371, 2015). "Understanding the impact of CDK5/p35 on Mφ polarization could have therapeutic implications, including anti-tumor responses, when it could maintain M1 but downregulate the M2 population." (PMID 41041338, 2025). "This suggests that the overall oncogenic output of Cdk5 may depend on the availability of its substrates; in many tumors, its pro-tumorigenic role may become dominant precisely because tumor-suppressive substrates like DLC1 are downregulated." (PMID 41369365, 2025). "Conversely, Cdk5 can also function to enhance anti-tumor immunity." (PMID 41369365, 2025). "These interactions might have important implications for the use of CDK5 inhibitors, which are already in clinical use for tumour diseases." (PMID 39739588, 2025). "Furthermore, the feasibility of combined targeting of LIMK1 and CDK5 for targeted therapy of tumor metastasis was investigated in a preclinical setting." (PMID 40476449, 2025). "CDK5 plays a central role in regulating immune checkpoints in tumor cells." (PMID 41561738, 2025). "Second, our current work demonstrates the essential role of LIMK1 and CDK5 in tumor metastasis." (PMID 40476449, 2025). "In tumor cells, CDK5 expression is crucial for IFNγ-induced CD274 expression." (PMID 41041338, 2025). "We confirmed that CDK5 phosphorylated KDR (Ser‐229) promotes tumor development." (PMID 38363020, 2024). "A previous study suggested that the anti-tumor immunity effects of CDK5 inhibition might be achieved by mediating the continuous expression of PD-L1 transcription inhibitors." (PMID 38960931, 2024). "Furthermore, cell cycle genes such as CDK5, CCNA2, CCNB1, and CCNB2, associated with tumor relapse and metastasis, are more highly expressed in DAB2IP-low Luminal A tumors." (PMID 39418101, 2024). "In a mouse tumor model, the inhibition of CDK5 expression or the combination of CDK5 inhibition with anti-PD-L1 therapy can significantly inhibit tumor growth and lead to increased levels of CD3+, CD4+, and CD8+ T cells in the spleen and decreased PD-1 expression in the CD4+ T cells." (PMID 38782996, 2024). "CDK5 ablation inhibited orthotopic tumor formation and systemic metastasis in vivo." (PMID 37993880, 2023). "Our data suggest that CDK5 has the potential to suppress IFN-β during VSV infection, and CDK5 expression is higher in most tumour cells than in normal cells, consistent with our conclusion that CDK5 enhances VSV infection by negatively regulating IFN-β production." (PMID 37332205, 2023).
tumor (continued). "Reduced expression of miR-152 that was observed in all ES cells allowed activation of CDK5 in the nucleus via the overexpression of p35 and p25, thereby indicating a relationship between the reduced expression of tumor suppressive miR-152 and continuous activation of CCNE through various factors." (PMID 37899376, 2023). "We hypothesize that Sn38 induces DNA damage in tumor cells, triggering the CDK5-mediated DNA damage repair pathway as a mechanism of resistance to repair the Sn38-induced DNA damage." (PMID 37511490, 2023). "Similarly, CDK5 inhibition or knockdown induces apoptosis in tumor spheres by stabilizing the transcription factor FOXO1." (PMID 37993880, 2023). "TTN-AS1, a tumor-promoting lncRNA, increases CDK5 expression in lung adenocarcinoma (LUAD)." (PMID 37993880, 2023). "Similarly, exogenous expression of nuclear CDK5 inhibits the proliferation of tumor cells and xenografts in nude mice." (PMID 37993880, 2023). "However, it is completely excluded from the nucleus of tumor cells, indicating that nuclear CDK5 acts as anti-oncogene." (PMID 37993880, 2023). "Moreover, as a crucial regulator of neuronal signal transduction, CDK5 can be found differentially expressed in gliomas, progressively augmenting with tumor grade, suggesting an active role not only in tumorigenesis but in aggressiveness as well." (PMID 36839989, 2023). "CDK5 increases its tumor suppressor activity by phosphorylating it at four serine residues namely S120, S205, S422 and S509 in the N-terminal region next to the Rho-GAP domain, which allows its binding to focal adhesions (talin, tensin) and increases its Rho-GAP activity." (PMID 37993880, 2023). "In tumor tissues, CDK5 was overexpressed compared to normal tissue." (PMID 37511490, 2023). "Aberrant overexpression of CDK5 significantly induces tumor cell motility and EMT in HNSCC." (PMID 37993880, 2023). "Alternatively, exporting tumor-suppressive nuclear substrates to the cytoplasm may also be an effective strategy to combat CDK5-induced oncogenicity." (PMID 37993880, 2023). "Finally, CDK5’s role as an oncogene or a tumor suppressor is defined by its access to distinct substrates." (PMID 37993880, 2023). "In addition, various CDK5 inhibitors have been used in preclinical trials for several types of tumours." (PMID 37332205, 2023). "The combination of increased CDK5 levels and oxaliplatin treatment repressed tumor growth by 79.0% compared to increased CDK5 levels alone, whereas oxaliplatin treatment alone moderately inhibited tumor growth in control cells (tumor inhibition rate = 50.2%)." (PMID 37990321, 2023). "The WNT pathway defines a molecular subgroup of MB; thus, it may be assumed that CDK5 might also contribute to this tumor malignancy." (PMID 36839989, 2023). "Interestingly, the presence of a set of downstream biomarkers of Cdk5 pathway activation was predictive of tumor growth inhibition in preclinical testing of a Cdk5-targeted therapy." (PMID 34862365, 2021). "Therefore, additional studies with fewer confounding factors must be conducted to confirm the expression level of CDK5 in both tumor and normal tissues." (PMID 34093802, 2021). "We also found that CDK5 was related to adverse outcomes and tumor metabolism." (PMID 34093802, 2021). "While the CRISPR/Cas9 plasmids could specifically target cyclin-dependent kinase 5 gene to mediate PD-L1 attenuation on tumor cells, so as to enhance anti-tumor immune response." (PMID 34095145, 2021). "Furthermore, we show the potential for Cdk5 to drive development of PanNETs by demonstrating that expression of the aberrant activator, p25, in islets of mice, initiates tumor formation." (PMID 34862365, 2021). "Moreover, it has been reported that CDK5 reduces the tumor inhibitory impact of BIN1 by regulating c-MYC Ser-62 phosphorylation in NSCLC." (PMID 34406978, 2021). "Inhibition of CDK5 reportedly impairs tumorsphere formation and reduces tumor establishment." (PMID 33960694, 2021).
tumor (continued). "Furthermore, CDK5 can promote tumor migration through the Ser425 phosphorylation of talin and the Ser732 phosphorylation of FAK (Focal adhesion kinase)." (PMID 35006426, 2021). "CDK5 appears to be an interesting and relevant target in oncology as previous preclinical studies suggested that CDK5 was integral in different tumor pathways, including tumor proliferation, migration, angiogenesis, DNA-damaging agent resistance and anti-tumor immunity." (PMID 32708903, 2020). "Moreover, high levels of CDK5 have been observed in different tumour types, and CDK5 was proposed to play various roles in the tumorigenic process." (PMID 31910742, 2020). "CDK5 may play a role in the anti-tumour immune response, by regulating the levels of programmed cell death ligand 1 (PD-L1) in tumour cells." (PMID 31910742, 2020). "Moreover, regulation of CDK5 by miRNA-26a has been shown to control cell proliferation, apoptosis and tumor growth in an animal model of diffuse large B-cell lymphoma." (PMID 33330110, 2020). "Expression of CDK5 is also regulated by the tumor suppressor miRNA-505-5p in cervical cancer cells." (PMID 33330110, 2020). "The results showed that multiple tumor nodules that had metastasized to the lung surface were observed in the control group, but none was seen in the CDK5‐KO group, while tumor volume and tumor weight were slightly reduced after CDK5 depletion." (PMID 33240752, 2020). "Moreover, similar to CDK5, pho‐PPARγ expression was mainly detected in the tumor tissues, especially in those of the late‐stage, as well as the lymph node with metastasis." (PMID 33240752, 2020). "Several studies postulated that CDK5 promotes tumour angiogenesis." (PMID 31910742, 2020). "Importantly, enhanced stemness transformation in tumor tissues after anti‐PD‐1 treatment was diminished markedly by CDK5 inhibition." (PMID 33240752, 2020). "Additionally, CDK5 promotes liver metastasis in subcutaneous xenotransplanted tumor model, demonstrating its effect in vivo." (PMID 31272499, 2019). "The results demonstrated that CDK5 knockdown could restore the tumor suppressing of BIN1 by inhibiting phosphorylation of c-MYC on Ser-62." (PMID 31496920, 2019). "A recent study discovered that knockdown of CDK5 can inhibit tumor growth in mouse model." (PMID 30704449, 2019). "In tumor tissues, Cdk5 is overexpressed compared to normal tissues due to a copy number gain." (PMID 31614664, 2019). "We further investigated the Cdk5 knockout (Cdk5+/−) transgenic mice with DEN-induced tumor model." (PMID 31272499, 2019). "To preliminarily clarify whether presence of CDK5 could act as tumor promoter by effecting the interaction of BIN1/c-MYC, we detected both CDK5 and BIN1 expression status in NSCLC cells." (PMID 31496920, 2019). "Taken above, these results revealed that presence of CDK5 could deactivate the tumor suppressing effect of BIN1 by mediating phosphorylation of c-MYC on Ser-62." (PMID 31496920, 2019). "Also, it has been demonstrated that Noxa is phosphorylated on both serine-13 and tyrosin-15 by the CDK5, resulting in prevention of the apoptotic function of Noxa in tumor cells." (PMID 31698798, 2019). "CDK5, an aberrantly overexpressed protein in multiple cancers, could significantly promote proliferation, invasion and migration abilities of tumor cells." (PMID 31496920, 2019). "Among the 107 tumor tissues, 61 cases (57.01%) showed positive staining of CDK5." (PMID 31363080, 2019). "Taken above, aberrant activation of CDK5 might be able to limit the tumor suppressing effect of BIN1 by blocking the BIN1/c-MYC interaction, consequently, overcoming the overexpression of CDK5 might further improve the prognosis of NSCLC patients." (PMID 31496920, 2019). "Whether patients with high Cdk5 tumor levels should be treated with irinotecan-based schedules rather than oxaliplatin-based schedules requires further investigation." (PMID 31614664, 2019).
tumor (continued). "CDK5 mRNA levels were significantly higher in primary tumor compared to normal colon." (PMID 29435174, 2018). "Moreover, RNA-seq data or microarray datasets from The Cancer Genome Atlas (TCGA) (HCC, n=374; normal, n=50) or other public databases (HCC, n=1864; non-tumor=1995) regarding CDK5 in HCC were extracted and examined." (PMID 29312535, 2017). "Because HCC is a highly vascularized tumor type, inhibiting CDK5 and therefore angiogenesis, could prove a promising treatment for this tumor subtype and other highly vascularized tumors." (PMID 28077789, 2017). "Previous studies have indicated that cyclin-dependent kinase 5 (CDK5), a serine/threonine protein kinase, is involved in tumor development and progression, and it may represent a potential therapeutic target." (PMID 28640256, 2017). "CDK5 and p35 were recently identified as a potent tumor suppressor in HCC." (PMID 29312535, 2017). "CDK5 expression in medulloblastoma allows tumor cells to evade detection by T-cells in vivo." (PMID 28077789, 2017). "Furthermore, ROC analysis was performed in our immunohistochemistry study and revealed that the CDK5 expression level was most useful in the diagnosis of tumor metastasis followed by tissue types, TNM stage, size, embolus and vaso-invasion." (PMID 29312535, 2017). "In recent years, studies have found that CDK5 was not only expressed in neurons, but also turned out to be of particular importance in non-neuronal cells, for instance: immune cells, endothelial cells, epithelial cells, tumor cells and so on." (PMID 27406233, 2016). "Here, by using the endothelial-specific Cdk5 knockout mouse models, endothelial and tumor cells, and human tumor xenografts, we investigate the heretofore unknown in vivo function of Cdk5 in the blood vessel endothelium." (PMID 26755662, 2016). "Here, we show that endothelial Cdk5 contributes to blood vessel development and tumor angiogenesis." (PMID 26755662, 2016). "CDK5-positive signaling located in the cytoplasm of the tumor cells." (PMID 26860827, 2016). "Together these findings suggest that aberrant CDK5 activity precedes cell cycle initiation and thus may function as a tumor-promoting factor facilitating cell cycle protein expression in MTC." (PMID 25900242, 2015). "Although several studies have established that miR-21 could promote EMT in tumor cells by a number of mechanisms, it is for the first time that we demonstrate CDK5 regulation by miR-21 to promote metastasis in HNSCC." (PMID 26690371, 2015). "Our results suggest that the miR-21/CDK5 axis could partially mediate tumor cell mobility and EMT by targeting STAT3 in HNSCC." (PMID 26690371, 2015). "Eight genes were downregulated after S6K1 silencing, but upregulated after S6K2 knock-down, among these the EGFR ligand amphiregulin (AREG), the glutamate-ammonia ligase (GLUL) involved in glutamine synthesis, and the CDK5 and ABL1 enzyme substrate 1 (CABLES1), implicated as a tumour suppressor." (PMID 26698305, 2015). "We find that downstream target genes of the tumor suppressor, retinoblastoma protein, including genes encoding cell cycle regulators such as CDKs, cyclins and CDK inhibitors, are significantly upregulated in malignant mouse tumors in a CDK5-dependent manner." (PMID 25900242, 2015). "Conversely, ectopic CDK5 overexpression significantly induced tumor cell motility and EMT." (PMID 26690371, 2015). "Moreover, CDK5 overexpression reverted the inhibition of EMT markers expression by asON and WP1066 in Hep-2 and Tca8113 cells, suggesting that CDK5 overexpression in HNSCC cells is sufficient to induce tumor cell motility via modulating EMT." (PMID 26690371, 2015). "Furthermore, CDK5 upregulation revealed a positive correlation with metastasis, vascular invasion, differentiation, advanced clinical stages, decreased survival and greater tumor recurrence." (PMID 37993880, 2023).